ABCA9 (ATP binding cassette subfamily A member 9)
Description:
Transporter that may play a role in monocyte differentiation and lipid transport and homeostasis.
Synonyms: EST640918
Tractability: Antibody: UniProt predicts a signal peptide or a membrane-spanning region; its Gene Ontology location is reachable by antibodies, with medium confidence.
Gene: Protein-coding gene on chromosome 17 (68,974,488 to 69,060,949, reverse strand). Ensembl gene ENSG00000154258.
Subcellular location: Membrane
Subcellular location (Human Protein Atlas): Endoplasmic reticulum
Pathways (Reactome):
Transport of small molecules: ABC transporters in lipid homeostasis
Gene Ontology:
Molecular function: ATPase-coupled transmembrane transporter activity; ABC-type transporter activity; ATP binding; ATP hydrolysis activity
Biological process: transmembrane transport
Cellular component: membrane; plasma membrane
Genetic constraint (gnomAD): Loss-of-function variants: 138 observed, 158.03 expected, observed/expected ratio (o/e) 0.87, 90% interval 0.76 to 1.01. The upper end of that interval is the gene's LOEUF score, 1.01, which puts it in group 4 of 6, group 1 being the genes least tolerant of losing a copy. Missense variants: 1,506 observed, 1,689.2 expected, observed/expected ratio (o/e) 0.89, 90% interval 0.85 to 0.93. Synonymous variants: 554 observed, 619.21 expected, observed/expected ratio (o/e) 0.89, 90% interval 0.83 to 0.96.
Homologues: Orthologues: chimpanzee ABCA9 (99% identical), macaque ABCA9 (96% identical), dog ABCA9 (86% identical), pig ABCA9 (83% identical), mouse Abca9 (79% identical), rat Abca9 (78% identical), guinea pig ABCA9 (78% identical), zebrafish abca5 (42% identical), Caenorhabditis elegans abt-4 (23% identical), Caenorhabditis elegans abt-2 (22% identical), Drosophila melanogaster Abca3 (22% identical), Drosophila melanogaster CG6052 (21% identical), and 9 more. Paralogues in human: ABCA8 (72% identical), ABCA10 (59% identical), ABCA6 (59% identical), ABCA5 (41% identical), ABCA1 (27% identical), ABCA4 (26% identical), ABCA2 (26% identical), ABCA3 (26% identical), ABCA7 (26% identical), ABCA12 (24% identical), ABCA13 (24% identical).
Diseases named in the same sentence as ABCA9 in open-access papers:
ABCA9 is named in the same sentence as 15 diseases in open-access papers, as found by Europe PMC text mining. Sharing a sentence is not in itself a finding about the gene and the disease. The quoted sentences say what the papers report.
breast carcinoma (5 papers, 2020 to 2025). "ABCA9 expression was downregulated in breast cancer cells and patient samples, and its restoration reduced proliferation and colony formation, and enhanced apoptosis." (PMID 40427160, 2025). "In a recent study, breast cancer cell lines MCF-7 and MDA-MB-231 showed increased copy numbers of ABCB1, ABCB4 (MCF-7 model), and ABCA9 (MDA-MB-231 model) to be associated with the formation of docetaxel resistance." (PMID 35631534, 2022). "The role of the ATP-binding cassette (ABC) transporters in tumorigenesis of White breast cancer patients is further supported by the enrichment of the “brown” module in basal transcription factors, including the ATP-binding cassette subfamily members ABCA9, ABCC9, ABCG2, ABCB1, ABCA6, and ABCA8." (PMID 32873298, 2020). "These investigators also found that ABCA9 is under the control of FOXO1 (tumor suppressor), which is downregulated in breast cancer, due to the activation of the PI3K–AKT pathway, which phosphorylates FOXO1." (PMID 40427160, 2025). "The cholesterol transporter ABCA9, which accumulates cholesterol in the endoplasmic reticulum (ER), reduces SREBP2 expression, thereby impairing breast cancer cell proliferation." (PMID 40308757, 2025). "Conversely, genes on chromosome 17 region “Nikolsky Breast Cancer 17q21-q25” were amplified in CR and contained ATP-binding cassette (ABC) transporters (ABCA5/ABCA6/ABCA8/ABCA9/ABCA10) among them (172 genes total, FDR = 7.39E−178)." (PMID 37012431, 2023).
abortion (1 paper, 2025). the ending of pregnancy by removing a fetus or embryo before it can survive outside the uterus. "Remarkably, CNVRs overlapped genes like ATP-binding cassette subfamily A member 9 (ABCA9), a member of the ABCA gene family responsible for regulating active transport in the placenta, which has been linked to abortion rate in Israeli dairy cattle." (PMID 40240941, 2025).
colorectal cancer (1 paper, 2025). A primary or metastatic malignant neoplasm that affects the colon or rectum. "Likewise, decitabine, a DNA methylation inhibitor, indirectly suppresses premetastatic niche formation in colorectal cancer by increasing the expression of ATP-binding cassette subfamily A member 9 (ABCA9)." (PMID 40270603, 2025).
dementia (1 paper, 2026). Loss of intellectual abilities interfering with an individual's social and occupational functions. "Abca9, along with other Abca-family genes, was recently identified as differentially expressed in superior frontal cortex and cerebellum of a younger-onset form of dementia when compared to controls." (PMID 41566221, 2026).
hepatocellular carcinoma (1 paper, 2025). A malignant tumor that arises from hepatocytes. "One study reported that in a subset of hepatocellular carcinoma human patients, ABCA8 and ABCA9 downregulation was significantly associated with shorter survival time." (PMID 40320296, 2025).
lung disorder (1 paper, 2022). A disease involving the lung. "ABCA3 has been pathologically linked to surfactant deficiency, a lung disorder relating to aberrant lipid transport that is fatal in newborns while there is very little knowledge on the physiological and pathological functions of ABCA9 and ABCA10." (PMID 36385764, 2022).
malignant melanoma (1 paper, 2012). "In addition, ABCA9, another membrane transporter linked to chemoresistance in some cancers like malignant melanoma, was found upregulated in the PDAC SP in our study." (PMID 22894607, 2012).
ABCA9 also shares sentences with these, for which no sentence is quoted: cancer (4 papers); tumor (2); brain tumors (1); frontotemporal dementia (1); gingival hyperplasia (1); lung carcinoma (1); neuroblastoma (1); skin disorder (1).